LTB4R2 (leukotriene B4 receptor 2)
Description:
Low-affinity receptor for leukotrienes including leukotriene B4. Mediates chemotaxis of granulocytes and macrophages. The response is mediated via G proteins that activate a phosphatidylinositol-calcium second messenger system. The rank order of affinities for the leukotrienes is LTB4 > 12-epi-LTB4 > LTB5 > LTB3.
Synonyms: LTB4-R 2; LTB4-R2; BLTR2; BLT2; JULF2; NOP9; KPG_004
Tractability: Small molecule: a drug acting on it is in phase 2 or 3 trials; a high-quality ligand is known; it belongs to a druggable protein family. Antibody: its Gene Ontology location is reachable by antibodies, with high confidence; UniProt places it where antibodies can reach, with medium confidence; UniProt predicts a signal peptide or a membrane-spanning region; the Human Protein Atlas places it where antibodies can reach. PROTAC: a small molecule that binds it is known. Other modalities: a drug acting on it is in phase 2 or 3 trials.
Target class: Leukotriene receptor; Small molecule receptor (family A GPCR); Membrane receptor; Lipid-like ligand receptor (family A GPCR); Family A G protein-coupled receptor
Gene: Protein-coding gene on chromosome 14 (24,305,734 to 24,312,053, forward strand). Ensembl gene ENSG00000213906.
Subcellular location: Cell membrane
Subcellular location (Human Protein Atlas): Plasma membrane; Nucleoplasm
Pathways (Reactome):
Signal Transduction: G alpha (q) signalling events; Leukotriene receptors
Gene Ontology:
Molecular function: protein binding; G protein-coupled peptide receptor activity; leukotriene B4 receptor activity; leukotriene receptor activity; G protein-coupled receptor activity
Biological process: chemotaxis; negative regulation of adenylate cyclase activity; neuropeptide signaling pathway; G protein-coupled receptor signaling pathway; leukotriene signaling pathway
Cellular component: membrane; plasma membrane
Genetic constraint (gnomAD): Loss-of-function variants: 8 observed, 7.05 expected, observed/expected ratio (o/e) 1.13, 90% interval 0.66 to 1.82. That is too few expected variants to judge how well the gene tolerates losing a copy. Missense variants: 560 observed, 475.17 expected, observed/expected ratio (o/e) 1.18, 90% interval 1.1 to 1.26. Synonymous variants: 310 observed, 239.03 expected, observed/expected ratio (o/e) 1.3, 90% interval 1.18 to 1.42.
Homologues: Orthologues: chimpanzee LTB4R2 (99% identical), macaque LTB4R2 (98% identical), rat Ltb4r2 (93% identical), mouse Ltb4r2 (92% identical), dog LTB4R2 (91% identical), pig LTB4R2 (91% identical), rabbit LTB4R2 (81% identical), tropical clawed frog ltb4r2 (39% identical), zebrafish ltb4r2a (34% identical), zebrafish ltb4r2b (30% identical), Drosophila melanogaster Rh7 (20% identical), Caenorhabditis elegans trhr-1 (16% identical). Paralogues in human: LTB4R (36% identical), PTGDR2 (28% identical), SSTR4 (24% identical), UTS2R (24% identical), OPRD1 (23% identical), SSTR1 (23% identical), SSTR5 (22% identical), OPRL1 (22% identical), NPBWR1 (22% identical), OPRK1 (22% identical), SSTR3 (21% identical), KISS1R (20% identical), and 5 more.
Diseases named in the same sentence as LTB4R2 in open-access papers:
LTB4R2 is named in the same sentence as 50 diseases in open-access papers, as found by Europe PMC text mining. Sharing a sentence is not in itself a finding about the gene and the disease. The quoted sentences say what the papers report.
asthma (11 papers, 2010 to 2025). "The aim of this study was to characterise the genes for the two pivotal LTB4 receptors, LTB4R1 and LTB4R2 in lung tissue and determine if polymorphisms spanning these genes are associated with asthma and disease severity." (PMID 23167751, 2012). "To date, little is known about the molecular structure of the two receptors for LTB4 (LTB4R1 and LTB4R2) in lung and peripheral cells/tissues and regarding the effect of polymorphism contributing to asthma and severity phenotypes." (PMID 23167751, 2012). "Proinflammatory signaling initiated by leukotriene LTB4 through its BLT1 and BLT2 receptors (encoded by LTB4R and LTB4R2 genes) is associated with various diseases, such as asthma, rheumatoid arthritis, atherosclerosis, abdominal aortic aneurysm, multiple sclerosis, and cancer." (PMID 33335138, 2020). "LTB4R2, as one of pivotal leukotriene B4 receptors, was proposed as potential therapeutic targets in asthma." (PMID 34809630, 2021). "Currently, relatively little is known about LTB4R1 and LTB4R2 gene structure, splice variation and polymorphic variation and the contribution of polymorphic variation to asthma and disease severity." (PMID 23167751, 2012). "The LTB4R2 gene is a pro-inflammatory lipid mediator that is only overexpressed under stress-induced inflammatory conditions and plays an important role in inflammatory diseases such as cancer and asthma." (PMID 35159340, 2022). "In the same line, LTB4R and LTB4R2, which are leukotriene B4 receptors (LTB4), have well-established roles in immunological diseases such as asthma." (PMID 41394805, 2025). "Our data suggest that LTB4R1 and LTB4R2 have complicated gene structure and are polymorphic and that polymorphisms spanning the LTB4R locus are not determinants of asthma susceptibility." (PMID 23167751, 2012).
breast carcinoma (11 papers, 2012 to 2023). "It was found that the overexpression of LTB4R2 is associated with the synthesis of interleukin-8 and increases invasion in aggressive breast cancer cell lines." (PMID 38139172, 2023). "We analyzed the TCGA BC expression dataset by dichotomizing the RNA-seq gene expression data using maximally selected rank statistics for determining the optimal threshold in order to assess the association of LTB4R and LTB4R2 expression levels with breast cancer patient survival." (PMID 38139172, 2023). "For instance, the leukotriene B4 receptor 2 (BLT2) is highly expressed in breast cancer tissues at both the mRNA and protein levels." (PMID 33498875, 2021). "In a recent study on an orthotopic breast cancer model, increasing the expression of the LTB4R2/LTB4/12(S)-HETE receptor system by lipopolysaccharide stimulation enhanced invasion of breast cancer cells, whereas its selective inhibition turned out in a reduced number of metastatic nodules." (PMID 27475906, 2016). "Among the features discriminating a moderately methylated triple negative breast cancer subtype (modTNBC) from all other BC methylotypes is the hypomethylation of a CpG island belonging to the leukotriene receptor 1 gene LTB4R and the leukotriene receptor 2 gene LTB4R2." (PMID 38139172, 2023).
colitis (4 papers, 2015 to 2025). Inflammation of the colon. "In a mice model, LTB4R2 was found to be expressed in colon cryptic cells and had a protective role against dextran sodium sulfate (DSS)-induced colitis, possibly by enhancing barrier function in epithelial cells of the colon." (PMID 27475906, 2016).
allergic asthma (3 papers, 2019 to 2024). A asthma with a basis in a pathological type I hypersensitivity reaction. "Additionally, a recent study investigating allergic asthma shows that TLR-4/LPS signaling modulates a leukotriene B4 receptor-2-mediated cascade in mast cells resulting in the release of the Th2 cytokine IL-1337." (PMID 31316085, 2019).
lung carcinoma (2 papers, 2021). "Through this approach, we identified and validated CSNK1A1, KDMA2, and LTB4R2 as new druggable vulnerabilities in lung cancer." (PMID 34298691, 2021). "Through this analysis, we identified CSNK1A1, KDM2A, and LTB4R2 as relevant druggable essentiality genes in lung cancer." (PMID 34298691, 2021). "We identified and validated a set of novel druggable non-oncogene vulnerabilities preferentially related to different lung cancer histotypes; dependency on KDM2A is associated with AD and SCLC, dependency on CSNK1A1 is associated with AD, and dependency on LTB4R2 is associated with SCC." (PMID 34298691, 2021). "We reasoned that CSNK1A1, KDM2A, and LTB4R2 dependencies could become therapeutic intervention points in lung cancer, so we proceeded with further characterization." (PMID 34298691, 2021). "Overall, in our study we described the use of an innovative integrative genomic approach to identify new candidate genes for lung cancer treatment, namely CSNK1A1, KDM2A, and LTB4R2." (PMID 34298691, 2021). "In addition, this strategy allowed us to identify three target genes that are poorly characterized and still require biological validation in lung cancer: CSNK1A1, KDM2A, and LTB4R2." (PMID 34298691, 2021).
Obesity (2 papers, 2020 to 2022). Accumulation of substantial excess body fat. "Except for LTB4R2, these genes have never been associated with obesity or NAFLD and could be therefore new candidates for these disorders." (PMID 31937803, 2020).
breast tumor (1 paper, 2019). "The authors showed that both leukotriene receptor Leukotriene B4 receptor 2 (BLT2) and Cysteinyl leukotriene receptor 2 (CysLT2) were expressed in human breast tumor and matched lymph node metastases." (PMID 31616408, 2019).
depression (1 paper, 2022). "Another tissue-specific gene, LTB4R2, in which the exon region was identified as the number one depression-related differential methylation region (P = 1.27 × 10–14)." (PMID 36081461, 2022).
esophageal squamous cell carcinoma (1 paper, 2016). Esophageal squamous cell carcinoma (ESCC) is a type of esophageal carcinoma (EC) that can affect any part of the esophagus, but is usually located in the upper or middle third. "Expression of LTB4R, LTB4R2, CYSLTR1 and CYSLTR2 was analyzed by immunohistochemistry (IHC) and quantitative reverse transcription-polymerase chain reaction (qRT-PCR) in biopsy samples of 19 patients with esophageal squamous cell cancer and 9 sex- and age-matched patients with functional dyspepsia." (PMID 27475906, 2016). "We aimed to investigate the expression of LTB4R, LTB4R2, CYSLTR1 and CYSLTR2 in esophageal squamous cell carcinoma and adjacent non-transformed squamous epithelium of the esophagus, as well as in control biopsy samples from esophageal squamous epithelium of patients with functional dyspepsia." (PMID 27475906, 2016).
leukemia (1 paper, 2025). A malignant (clonal) hematologic disorder, involving hematopoietic stem cells and characterized by the presence of primitive or atypical myeloid or lymphoid cells in the bone marrow and the blood. "A half of these proteins have no reported relationship with leukemia, i.e., LTB4R2, DDX39B, ZNF668, ZNF788, and DXO." (PMID 40699783, 2025).
ovarian carcinoma (1 paper, 2020). A malignant neoplasm originating from the surface ovarian epithelium. "In cisplatin-resistant ovarian cancer cell line SKOV-3, upregulation of leukotriene B4 and its receptor leukotriene B4 receptor-2 (BLT2) leads to activation of STAT-3 and IL-6 and depletion of BLT2 increased cell sensitivity to cisplatin chemotherapy." (PMID 32982722, 2020).
skin infection (1 paper, 2018). An inflammatory process affecting the skin, caused by bacteria, viruses, parasites, or fungi. "We first measured the mRNA transcript levels for Alox5 (the gene that encodes 5-LO), Ltb4r1 (the gene that encodes BLT1), and Ltb4r2 (BLT2) during MRSA skin infection." (PMID 30102746, 2018). "At 1 day post-MRSA skin infection, the expressions of Alox5 and Ltb4r1, but not Ltb4r2, were significantly enhanced in the skin of infected mice compared to naïve mice skin." (PMID 30102746, 2018).
tumor (20 papers, 2008 to 2025). "Tumor suppression is associated with reduced leukotriene B4 receptor 2 (LTB4R2) and its high affinity oxylipin ligand, 12-hydroxyheptadecatrienoic acid (12-HHTrE)." (PMID 37156770, 2023). "The tumor-promoting role of aHSC SCD-CYP1B1-tumor LTB4R2 pathway was supported by tumor suppression in mice by conditional Scd2 ablation and AAV8-based Ltb4r2 KD." (PMID 37156770, 2023). "We suggest that LTB4R2 activation by 12-HHTrE produced by aHSC CYP1B1 causes CTNNB1 activation via GSK3β pathway and subsequent YAP1 transcription and tumor promotion." (PMID 37156770, 2023). "A population of CYP1B1-expressing aHSC in TME is relatively small but likely upregulates LTB4R2 in adjacent tumor cells via paracrine positive-forward regulation of the receptor that we disclosed." (PMID 37156770, 2023). "aHSC release 12-HHTrE in a manner dependent on SCD and CYP1B1 and their conditioned medium reproduces the LTB4R2-mediated tumor-promoting effects of 12-HHTrE in HCC cells." (PMID 37156770, 2023). "Upregulation of LTB4R/LTB4R2 in a subset of TNBC samples suggests that the expression levels of these receptors may be employed in the future as a marker of tumor sensitivity to leukotriene receptor inhibitors." (PMID 38139172, 2023). "The KD appeared to reduce liver weight/body weight ratio and significantly suppressed tumor multiplicity and total tumor volume, reproducing the phenotype observed in the Scd2f/f;CC mice and validating the role of LTB4R2 in CTNNB1 and YAP1 activation and liver tumorigenesis in vivo." (PMID 37156770, 2023). "Furthermore, neutrophils endorse the proliferation and colonization of leukotriene B4 receptor 2 (LTB4R2)-positive disseminated tumor cells, thereby impacting metastasis." (PMID 34885082, 2021). "TGF-β induced EMT mediated by inflammatory cells in the tumor microenvironment is promoted by leukotriene B4 receptor 2, which, in response to leukotriene B4, activates reactive oxygen species (ROS) and NF-κB transcriptional activity that facilitates the establishment of EMT by TGF-β42." (PMID 32439908, 2020). "Splenic macrophages (F4/80+ CD11blow) which had become activated by PIFAs via leukotriene B4 receptor 2 (BLT2) secreted polyunsaturated lysophosphatidylcholines (LPCs) which were capable of altering the DNA damage response in the distant tumor, and conferred therapy resistance." (PMID 31379850, 2019). "Genetic or pharmacological inhibition of LTB4R2 recapitulates CTNNB1 and YAP1 inactivation and tumor suppression in culture and in vivo." (PMID 37156770, 2023). "To validate the dependency of tumor cells on CSNK1A1, KDM2A, and LTB4R2 in vitro, we generated the knockout (KO) of each gene by independently introducing two sgRNAs in two AD cell lines, NCI-H23 and A549." (PMID 34298691, 2021). "This analysis identified three genes expressed in tumor cells, i.e. ALOX15B, the leukotriene B4 receptor gene LTB4R2 and the PGE2 receptor gene PTGER3." (PMID 27215396, 2016).
cancer (19 papers, 2008 to 2025). A tumor composed of atypical neoplastic, often pleomorphic cells that invade other tissues. "All GBM lines express LTA4H, LTB4R1/BLT1, LTB4R2/BLT2, and CysLTR2, but only some lines express LTC4S, indicating heterogeneity in the production of cysteinyl-leukotrienes and 5-HETE by GBM cancer cells." (PMID 36765904, 2023). "Protein expression of LTB4R2 and CYSLTR2 was found to be significantly increased in cancer tissue compared to normal mucosa of cancer group and control (p < 0.05)." (PMID 27475906, 2016). "IRS of LTB4R2, CYSLTR1 and CYSLTR2 receptors were medium in cancer tissue but low in normal epithelium of cancer patients and control basal stratum." (PMID 27475906, 2016).
lung (1 paper, 2021). "Notably, LTB4R2 was also identified in our previous work as a dependency gene specifically associated with the KRAS-mutated background in lung AD." (PMID 34298691, 2021).
LTB4R2 also shares sentences with these, for which no sentence is quoted: prostate carcinoma (4 papers); atherosclerosis (3); inflammation (3); pancreatic cancer (3); Arthritis (2); infection (2); lung adenocarcinoma (2); abdominal aortic aneurysm (1); acute respiratory failure (1); Allergy (1); apical periodontitis (1); autoimmune disease (1); autoimmune thyroid disease (1); bladder cancer (1); carotid atherosclerosis (1); chronic pancreatitis (1); colon cancer (1); diabetes (1); eosinophilia (1); functional dyspepsia (1); gastric cancer (1); hyperglycaemia (1); influenza infection (1); intracerebral hemorrhage (1); lung injury (1); lymph node metastasis (1); metabolic syndrome (1); metastatic cancer (1); multiple sclerosis (1); oesophageal cancer (1).
A further 5 diseases each share a sentence with LTB4R2 in 1 paper.